CD248 (CD248 molecule)
Diseases named in the same sentence as CD248 in open-access papers (continued):
Sharing a sentence is not in itself a finding about the gene and the disease.
tumor (continued). "Herein, we examined CD248 expression from CAFs derived from NSCLC patient tumour tissues." (PMID 38906929, 2024). "In mouse models CD248 KO has been shown to have tumor abrogating effects via vascular depletion." (PMID 38468017, 2024). "Evidence suggesting CD248 expression on naïve T cells is another potential avenue for further study, as CD248 expression on T cells could be a means of tumor-driven immunosuppression, and therefore a potential novel target for immunotherapy." (PMID 38468017, 2024). "To determine whether CD248 affects tumour metastasis in vivo, we injected LLC cells into the tail veins of cd248fl/flfsp‐1+/+ (WT) and cd248fl/flfsp‐1cre/+ (cKO) mice." (PMID 39164826, 2024). "Third, according to our RNA-seq data, CD248 may regulate multiple signaling pathways that is related with tumor progression." (PMID 36997926, 2023). "While thrombomodulin, CD93 and CLEC14A are mainly expressed by endothelial cells, CD248 is expressed by vasculature-associated pericytes, activated stromal fibroblasts, mesenchymal stem cells and tumor cells, but not in the endothelium." (PMID 37443812, 2023). "Taken together, we disclosed the different immune characterization in two major and five rare DC subtypes, and revealed the unique profiles of four immune clusters, providing the potential managements of CD248 in the Cold tumor cluster and CD276/CAR-T in the Hot tumor cluster." (PMID 36991000, 2023). "CD248 expression has also been observed in some tumor cells." (PMID 36401329, 2022). "The lectin domain at the N-terminal of CD248 may enhance the adherence of tumor cells to fibronectin, whereas its C-terminal cytoplasmic domain may anchor to F-actin, thereby forming a linkage between F-actin and ECM proteins." (PMID 36401329, 2022). "By cross-talking with both pro- and anti-angiogenic signals and extracellular matrix components, and participating in dynamic vascular remodelling, CD248 could facilitate tumour growth." (PMID 35708873, 2022). "In contrast, CD248 expression in some cancer cells may contribute to tumor progression through autonomous effects." (PMID 36401329, 2022). "In this study, we found that tumor cells with autonomous CD248 expression exhibited VM expression potential to support blood supply in the tumor and promoted tumor growth and metastasis; therefore, CD248 expression might contribute to tumor malignancy." (PMID 36401329, 2022). "Since both CD248 and CAFs were associated with immunoregulation, the CD248+ CAF-mediated RCC tumor-promoting effect may be involved." (PMID 34970489, 2021). "Moreover, the increase of CD248+ CAFs in the tumor reflected the complexity of TME components, in which there was an increase in the stromal and immune ingredients and was accompanied by the proliferation of epithelial cells." (PMID 34970489, 2021). "As a result, several hub DEFs with maximum intramodular connectivity were identified (e.g., SOX4, EGR1, LEF1, FOS, MITF, KLF4, TCF7, and KDM6B), which might involve CD248-mediated tumor-promoting regulation in CAFs." (PMID 34970489, 2021). "First, the sample size was relatively small, especially for advanced or metastatic cases, which might be the reason why CD248 expression didn’t show significant difference in tumor metastasis and tumor invasion." (PMID 34869004, 2021). "In addition, the knockdown of CD248 in mice showed significant suppression mediated by stromal cells in tumor growth, invasion, and metastasis following tumor transplantation." (PMID 34970489, 2021). "It is believed that CD248 is involved in the tumor vasculature." (PMID 34207884, 2021). "Therefore, CD248-characterized tumor vasculature and stroma were regarded as promising targets for the therapy of tumors." (PMID 33791227, 2021). "Finally, sustaining proliferative signatures and evading growth suppressors to facilitate tumor disordered amplification is another pathway that CD248+ CAFs use to facilitate tumor progression." (PMID 34970489, 2021).
tumor (continued). "As a result, CD248+ CAFs might influence immunity, stromal-related signatures, cell adhesion, cell cycle, and metabolism to promote tumor deterioration." (PMID 34970489, 2021). "CD248 may serve as a promising CAFs biomarker and be involved with the tumor-promoting effect of CAFs." (PMID 34970489, 2021). "Considering that the prognostic value of both CD248 and CAFs was related to the TME, together with our previous findings that CD248 contributes to tumor-promoting regulation of CAFs in HCC, we proposed to explore the relationship between CD248 and CAFs in RCC progression." (PMID 34970489, 2021). "CD248 is a transmembrane receptor with ligands that include collagen 1 and are upregulated by inflammation in inflammatory reactions; recent studies indicate that overexpression of CD248 can be differentiated into tumor stromal fibroblasts." (PMID 33748448, 2021). "Prophylactic immunization of mice with CD248-TT prevented or delayed tumor formation in mice." (PMID 30847027, 2019). "So far clinical trials targeting CD248 have proved to be very disappointing, and such agents may only be effective in certain tumour types or may need to be combined with other therapeutics for optimal clinical benefit." (PMID 31287944, 2019). "Within tumor stroma, pericytes and myofibroblasts have upregulated CD248 expression." (PMID 30847027, 2019). "CD248-expressing pericytes in the tumor facilitated distant site metastasis by promoting tumor cell intravasation in a cell contact–dependent manner, resulting in higher circulating tumor cells." (PMID 30847027, 2019). "In carcinomas, CD248 protein was detected in tumor capillaries and fibroblasts." (PMID 30847027, 2019). "The anti-CD248-MC-VC-PABC-MMAE conjugate produced marked prolonged tumor responses in both models." (PMID 30847027, 2019). "Finally, CD248/endosialin/TEM1 is present in a variety of tumor environments, with little expression on normal tissues, and has shown potential as a sarcoma target in early studies." (PMID 31311607, 2019). "Anti-CD248 imaging can detect and monitor tumor responses and select patients who may benefit from CD248-targeted therapies." (PMID 30847027, 2019). "Subsequent and more refined studies found CD248 was specifically expressed on tumor-associated pericytes and stromal cells, but not directly by tumor-associated endothelial cells." (PMID 26327620, 2015). "Although MORAb-004 can cause internalization and reduction of CD248 levels on in vitro cultured human brain pericytes, its effect on cell surface CD248 levels of tumor microvessels has not been previously documented." (PMID 26327620, 2015). "Thus, with the switch from a tumor suppressor to a tumor promoter, TGFβ loses it ability to regulate CD248." (PMID 24555435, 2014). "The findings suggest that CD248 not only promotes tumorigenesis, but may be a marker of the transition of TGFβ from a tumor suppressor to a tumor promoter." (PMID 24555435, 2014). "Upregulation of CD248 might be an early detection marker of tumor growth and metastasis, and may be valuable in monitoring TGFβ-based therapies." (PMID 24555435, 2014). "By contrast, CD248 has been shown to be a fairly selective marker present in stromal fibroblasts and pericytes within proliferating tissues such as inflammatory lesions, lymphoid tissues, foetal tissues and tumours." (PMID 23363614, 2013). "Regarding the amplified genes, CD248 (TEM-1) amplification in 11 samples might be justified by its established role in tumor angiogenesis." (PMID 22879877, 2012). "Thus, it is likely that the cytoplasmic domain of CD248 facilitates fibroblast release of soluble factors that promote tumor growth." (PMID 21549007, 2011). "To test this hypothesis, we first validated the role of CD248 in tumor growth in CD248KO/KO mice, comparing the response with corresponding CD248WT/WT mice." (PMID 21549007, 2011). "CD248 is also expressed in human mesenchymal stem cells from bone marrow, which may differentiate into tumor stromal fibroblasts." (PMID 21549007, 2011).
tumor (continued). "Since SM22α is co-ordinately regulated by Notch and TGF-β, we hypothesized that the cytoplasmic domain of CD248 would similarly regulate expression of Hes and Hey1, downstream effectors of Notch that also exhibit context-specific tumor suppressor properties." (PMID 21549007, 2011). "Few analyses have been performed to elucidate the mechanisms by which CD248 regulates tumor growth." (PMID 21549007, 2011). "The findings are confirmatory of an important role for CD248 in tumor growth." (PMID 21549007, 2011). "Others have reported that CD248 gene inactivation in mice results in dampened tumor growth." (PMID 21549007, 2011). "We hypothesized that the conserved cytoplasmic domain of CD248 is important in regulating tumor growth." (PMID 21549007, 2011). "Indeed, Hes and Hey1 transcript levels in CD248CyD/CyD fibroblasts were significantly higher than in CD248WT/WT fibroblasts, in line with the role of CD248 in promoting tumor growth." (PMID 21549007, 2011). "While several investigators have shown that CD248 plays an important role in tumor growth and stromal expansion with expression levels that have been correlated with tumor progression, the mechanisms by which CD248 functions and the key structural domains involved, have remained a mystery." (PMID 21549007, 2011). "Notably, we did not observe an inverse relationship between vessel density and tumor size in our studies with the CD248CyD/CyD versus CD248WT/WT mice, findings that contrast with those reported in studies using CD248-deficient mice." (PMID 21549007, 2011). "We recently reported that CD248CyD/CyD fibroblasts express reduced amounts of VEGF, PlGF and active MMP-9 and considered that other soluble factors might be secreted in a CD248-dependent manner that regulate tumor cell proliferation." (PMID 21549007, 2011). "However, the role that CD248+ PCs play on tumor is less studied than CD248+ fibroblasts." (PMID 40248695, 2025). "In addition, CD248 interacted with 11 common tumor biomarkers." (PMID 40276611, 2025). "In summary, the differential expression of CD248 across tumors may result from a combination of factors, including the tumor microenvironment, tissue origin, immune microenvironment, epigenetic regulation, and tumor subtypes." (PMID 40276611, 2025). "In our previous study, we demonstrated that CD248 expression in NSCLC‐based CAFs was associated with the adverse patient outcomes and clinicopathological features of NSCLC, including tumour differentiation and staging, lymph node metastasis, and tumour‐node‐metastasis (TNM) staging." (PMID 39164826, 2024). "Additionally, the high density of CD248 + mr-CAFs formed a protective niche for tumor cells." (PMID 39334513, 2024). "However, the anti-proliferative role of CD248 on CD8 + T cells has not been demonstrated given the lack of expression on murine T cells nor is it known if tumor associated CD8 + T cells express CD248 differentially than other effector T cells." (PMID 38468017, 2024). "Though we have demonstrated that CD248 expression level was associated with several cellular activities, whether CD248-mediated VM is responsible for tumor progression has not been directly tested in the current study." (PMID 36401329, 2022). "Additionally, forming and remodeling the ECM to block normal immune cell infiltration and facilitating the invasion of epithelial cells might be another mechanism by which CD248+ CAFs promote tumor progression." (PMID 34970489, 2021). "In this study, the association between CD248 expression and the Ki-67 index could partially indicate a correlation with tumor metastasis and tumor invasion, although the association was not statistically significant." (PMID 34869004, 2021). "Additionally, increased CD248+ CAF infiltration could indicate worse tumor stage, local invasion, and metastasis of RCC (p < 0.01)." (PMID 34970489, 2021). "However, CAF-mediated tumor progression and the potential mechanism of CD248 remain largely unknown in RCC patients." (PMID 34970489, 2021).
tumor (continued). "Furthermore, such targeting strategies may destabilise the binding of CD248 expressing pericytes to the tumour vasculature, although whether this affects pericyte coverage remains to be investigated." (PMID 31287944, 2019). "Therefore, delineating the hitherto unknown mechanisms by which CD248 regulates tumor growth is important for the development of therapeutic strategies." (PMID 21549007, 2011). "CD248 is now recognized to be primarily expressed on the surface of mesenchymal stem cells, activated stromal fibroblasts and pericytes, cells that may contribute to fibrovascular network expansion and tumor progression." (PMID 21549007, 2011). "Immunofluorescence staining for CD248, PD-L1, CD3, and CD8 in tumor sections showed reduced CD248 and PD-L1 expression in both untreated and treated cKO mice, along with greater CD8+ T cell infiltration in the tislelizumab-treated cKO group." (PMID 40735646, 2025). "Tumor tissues and matched NAT were obtained from NSCLC patients and subjected to immunohistochemical staining for CD248 and PD-L1." (PMID 40735646, 2025). "However, whether CAFs that express CD248 influence tumor immune escape remains unclear." (PMID 40735646, 2025). "In tumor-bearing mice, lung tumors grew significantly slower, and the amount of granzyme B+CD8+T cells was greater in fibroblast-specific CD248 gene knockout mice than in wild-type mice." (PMID 40735646, 2025). "Based on our findings, tumour development was strongly (p < 0.05) enhanced by the A549 and CAFs‐sh‐CON cell combination, relative to the A549 and CAFs‐sh‐CD248 cell combination." (PMID 38396325, 2024). "The findings revealed that COL1A1 expression correlated with CD248 expression in LUAD and LUSC tumour tissues relative to that in NAT tissues." (PMID 39164826, 2024). "TEM1 (tumor endothelial marker 1), also known as endosialin or CD248, is dynamically expressed on pericytes, fibroblasts of tumor stroma, but barely expressed in benign and normal tissues." (PMID 36639546, 2023). "A DNA-based vaccine approach demonstrated that CD248 can be effectively targeted immunologically; anti-tumor responses were generated in several mouse models; and CD8+/CD4+ T cell responses were elicited against peptides derived from CD248 protein." (PMID 30847027, 2019). "Each family member has strong links to tumour development and in particular CD93, CLEC14A and CD248 have been proposed as attractive candidate targets for cancer therapy." (PMID 31287944, 2019). "Not only were both CD248 and α-SMA co-expressed on pericytes on control tumor microvessels, their cellular distribution patterns were similarly polarized to the basal side of pericytes towards the endothelium." (PMID 26327620, 2015). "Also, we identify stromal antigens, previously targeted to manipulate the TME, as tumor cell intrinsic in STS like FAP, FOLR2, or CD248." (PMID 40814001, 2025). "E3K CAR T-cells showed specific killing activity against CD248-positive cells in three immunocompetent mouse models (BALB/c, FVB/N, and C57BL/6), effectively clearing target cells from the TME, resulting in increased tumor necrosis and growth inhibition." (PMID 41226585, 2025). "The majority of tumour neovascular endothelial cells express CD248, while normal vascular endothelial cells do not." (PMID 39164826, 2024). "Unlike CD93 and CLEC14a but like CD248, expression of TM on tumor cells themselves seems to carry more relevancy to cancer biology than angiogenesis." (PMID 38468017, 2024). "Site specificity regarding response to CD248 knockdown in murine tumor implantation has been reported, citing lack of anti-tumor response in subcutaneously implanted tumors compared to abdominally implanted ones." (PMID 38468017, 2024). "CD248, otherwise called endosialin or tumour endothelial marker 1(TEM1), does not typically express in healthy tissues, and is ubiquitous in stromal cells, such as, activated fibroblasts, tumour perivascular cells or during inflammatory diseases." (PMID 38396325, 2024).
tumor (continued). "Among these, CD273 and CD146 may indeed be MSC-specific, whereas CD36 (a receptor for thrombospondin-1), CD200 (also expressed on tumor cells), CD274 (PDL-1), and CD248 (endosialin) are also expressed in fibroblasts, often in a tumor context." (PMID 39201399, 2024). "The authors concluded that rather than intrinsically altering tumor cell metastatic potential, CD248 expressing pericytes facilitate metastasis by mediating transmigration through basement membrane and into the endothelium." (PMID 38468017, 2024). "The majority of tumor neovascular endothelial cells express CD248 and not normal vascular endothelial cells." (PMID 38906929, 2024). "CD248 promotes tumor progression through both tumor cell-autonomous and non-cell-autonomous effects." (PMID 36401329, 2022). "Through a non-autonomous effect, stromal CD248 can promote tumor progression by modulating the tumor microenvironment." (PMID 36401329, 2022). "As a result, the infiltration of tumor epithelial cells, cytotoxic T cells, natural killer (NK) cells, monocytic macrophages, myeloid dendritic cells (MDCS), endothelial cells (ECs), and CAFs was increased in the CD248 high-expression group." (PMID 34970489, 2021). "We have previously confirmed that CD248 represents a promising biomarker of CAFs, which may provide insight into CAF-based tumor-promoting effects." (PMID 34970489, 2021). "Upregulation of PD‐L1, CD90, PDGFRβ, CD248 and Rgs5 which inhibit CD4+ and CD8+ cytotoxic T‐cell activity was reported in pericytes derived from within tumour microenvironments, which facilitates immunosuppression and eventual immune evasion of tumour cells." (PMID 32588948, 2020). "Besides, CD248 enhanced the adhesion to the extracellular matrix, and activated the matrix metalloproteinase 9 (MMP9) in tumor metastasis." (PMID 33585235, 2020). "We isolated from growing tumors of the 3 different cell lines, green fluorescent tumor cells that simultaneously expressed two endothelial cell markers (CD31 and CD105) or two pericyte markers (CD146 and CD248) and used them, as well as the corresponding depleted cell pools, to produce tumorspheres." (PMID 31267022, 2019). "CD248 expression in stroma increased from normal mucosa to tumor both in radiotherapy-treated and non-radiotherapy-treated tumors." (PMID 30847027, 2019). "Interestingly, a characteristic feature identified in CHO cells overexpressing CD248 is the upregulation of MMP9, thereby implicating CD248 in ECM degradation, a key step in sprouting angiogenesis as well as tumour metastasis and invasion." (PMID 31287944, 2019). "This was presumably due to increase in microvessel density and the presence of nonfunctioning tumour blood vessels; phenocopying previous findings in CD248 knockout animals." (PMID 31287944, 2019). "CD248 expression was present in 86% of the stage IV tumor microarray specimens, and there was no expression in the normal tissue controls." (PMID 30847027, 2019). "CD248 (also termed Endosialin and TEM-1), is a heavily glycosylated transmembrane protein that was identified initially as a cell surface marker overexpressed in tumour vasculature." (PMID 27080864, 2016). "Concurrently, expression of CD248 dropped from the highest level on pericytes surrounding tumor microvessels to completely negative when the pericytes differentiated into smooth muscle cells as the blood vessels grew larger into a more artery-like structure." (PMID 26327620, 2015). "In contrast, we observed an average 80% reduction of CD248 expression levels on MORAb-004 treated tumor pericytes, with the vast majority being completely negative for cell surface expression." (PMID 26327620, 2015). "Mice lacking the cytoplasmic domain of CD248 (CD248CyD/CyD) were generated and evaluated in tumor models, comparing the findings with wild-type mice (CD248WT/WT)." (PMID 21549007, 2011).